OR51I1 (olfactory receptor family 51 subfamily I member 1)
Description:
Odorant receptor.
Tractability: Antibody: UniProt places it where antibodies can reach, with medium confidence; UniProt predicts a signal peptide or a membrane-spanning region; its Gene Ontology location is reachable by antibodies, with medium confidence.
Gene: Protein-coding gene on chromosome 11 (5,440,570 to 5,441,514, reverse strand). Ensembl gene ENSG00000167359.
Subcellular location: Cell membrane
Pathways (Reactome):
Sensory Perception: Expression and translocation of olfactory receptors
Gene Ontology:
Molecular function: olfactory receptor activity; G protein-coupled receptor activity; signaling receptor activity
Biological process: sensory perception of smell; cellular response to lipid; detection of chemical stimulus involved in sensory perception of smell; G protein-coupled receptor signaling pathway; system process
Cellular component: membrane; plasma membrane
Genetic constraint (gnomAD): Loss-of-function variants: 6 observed, 11.16 expected, observed/expected ratio (o/e) 0.54, 90% interval 0.29 to 1.06. The upper end of that interval is the gene's LOEUF score, 1.06, which puts it in group 4 of 6, group 1 being the genes least tolerant of losing a copy. Missense variants: 465 observed, 410.54 expected, observed/expected ratio (o/e) 1.13, 90% interval 1.05 to 1.22. Synonymous variants: 183 observed, 148.99 expected, observed/expected ratio (o/e) 1.23, 90% interval 1.09 to 1.39.
Homologues: Orthologues: mouse Or51i1 (88% identical), rat Or51i1 (88% identical), pig OR51I1 (87% identical), rabbit OR51I1 (80% identical). Paralogues in human: OR51I2 (59% identical), OR51G2 (52% identical), OR51G1 (51% identical), OR51F2 (50% identical), OR51L1 (49% identical), OR51A7 (47% identical), OR51M1 (47% identical), OR51A4 (47% identical), OR51Q1 (47% identical), OR51E1 (46% identical), OR51A2 (46% identical), OR51C1 (46% identical), and 39 more.